CD4 (CD4 molecule)
Diseases named in the same sentence as CD4 in open-access papers (continued):
Sharing a sentence is not in itself a finding about the gene and the disease.
HIV-1 infection (continued). "Between the two forms of 2G12, the monomer had a minimal effect at preventing the loss of CD4+ and CD8+ splenocytes following HIV-1 infection, whereas the 2G12 dimer was able to rescue nearly half of the CD4+ cells and most of CD8+ cells in the spleen." (PMID 21187894, 2010). "Haematopoïtic cells (HPC) have also been proposed to serve as a viral reservoir, since a subpopulation of CD34+ HPCs express CD4 and CCR5 and/or CXCR4 and these cells are susceptible to HIV-1 infection." (PMID 20380694, 2010). "In vivo HIV-1 infection results in a distinctive mRNA transcriptome profile in CD4+ T cells that involves 260 genes in an analysis that differentiates individuals with high and those with low viral setpoint." (PMID 20195503, 2010). "A number of groups including ours have demonstrated the utility of these humanized mice as improved models for HIV-1 infection and CD4 T cell depletion." (PMID 21203568, 2010). "As a control, we also used CEM T-cells, a CD4+ human T-lymphoblastoid cell line that is often used for HIV-1 infection and production studies." (PMID 21126372, 2010). "In M12020 the compartmentalization of effector memory-derived virus pre-therapy indicates that in the case of dual HIV-1 infection one strain preferentially infects a specific CD4+ lymphocyte subset." (PMID 21134247, 2010). "During the course of disease, the human immune system engages in a pitched battle with the virus, however the potent CD4+ T cell responses that are elicited are the very thing that provides the fuel for HIV-1 infection." (PMID 21994702, 2010). "Early steps of HIV-1 infection include viral entry by binding to the main receptor CD4 and either of two co-receptors CCR5 or CXCR4." (PMID 21129188, 2010). "This mouse model supports human hematopoietic development, provides human CD4 T cells as natural targets of HIV-1 infection, and allows for possible selection of viral resistance." (PMID 21187894, 2010). "The CD4+ lymphocyte is the main target cell for HIV-1 infection with the various sub-populations infected to a different extent." (PMID 21134247, 2010). "We have demonstrated that palmitic acid is a novel class of small molecule that binds to the CD4 receptor and blocks gp120-to-CD4 fusion and HIV-1 infection." (PMID 20730055, 2010). "Coculture of transfected Jurkat T cells and target Raji/CD4 B cells enhanced HIV-1 infection two fold and HTLV-1 infection ten thousand fold in comparison with cell-free infection of Raji/CD4 cells." (PMID 20195464, 2010). "We studied the effect of antiretroviral therapy on HIV-1 infection levels of naïve, central memory and effector memory CD4+ lymphocyte populations and on the viral quasi-species present in these subsets, two to five weeks after initiation of ART." (PMID 21134247, 2010). "Earlier studies showed that HIV-1 infection in quiescent CD4+ T-cells results in 4-fold lower levels of viral entry, and incomplete reverse transcription and minimum levels of integration are observed." (PMID 19300495, 2009). "In this report, we show that soluble mimics of CD4 inhibit HIV-1 infection by prematurely triggering the viral envelope glycoproteins." (PMID 19343205, 2009). "HIV-1 infection was associated with low antibody levels to AMA-1 and, among HIV-1 infected adults, low AMA-1 antibody levels were associated with low CD4 count." (PMID 19922664, 2009). "The establishment of a stable HIV-1 infection and a steady decline in CD4+ T cell counts resulted in one of the most efficient humanized mouse models of HIV-1 infection to date." (PMID 19674458, 2009). "The most interesting aspect of HIV-1 infection in DCs is the ability of the cells to act as mediators of trans infection of activated CD4+ T cells, which is the most productive cell type for viral replication." (PMID 19486514, 2009).
HIV-1 infection (continued). "Additional studies indicated that both HIV-1 infection of DCs and DC-mediated virus transmission to CD4+ T cells were reduced upon TLR4 triggering due to secretion of type-I interferons." (PMID 19419540, 2009). "The vast majority of studies that have contributed to our current understanding of CD4+ T cell immunology in HIV-1 infection have been conducted in the context of clade B infection, which is the predominant clade in North America and Europe." (PMID 19352428, 2009). "Jekle and colleagues established that depletion of CD4+ T lymphocytes by HIV-1 infection in HLAC predominantly results from the killing of uninfected bystander cells." (PMID 19146681, 2009). "CTLA-4 is upregulated in HIV-specific CD4+ T cells, particularly in patients with chronic HIV-1 infection." (PMID 20016783, 2009). "Early HIV-1 infection is characterized by the death of both infected and uninfected CD4+ T cells, often resulting in extensive CD4+ T cell depletion in the gastrointestinal tract." (PMID 19582166, 2009). "This quantitative review confirmed that RNA and CD4 have very different time patterns of clinical prognostic value during untreated HIV-1 infection." (PMID 19536329, 2009). "Persistent HIV-2 infection is thought to induce a chronic stimulation of the immune system leading to a progressive T cell impairment and CD4 depletion, though at much slower rates than in HIV-1 infection." (PMID 19936055, 2009). "Although soluble CD4 (sCD4) typically inhibits HIV-1 infection of CD4+CCR5+ cells, enhancement of HIV-1 infection of CCR5+ cells lacking CD4 is sometimes seen after sCD4 treatment." (PMID 19343205, 2009). "During HIV-1 infection, CD4 and CCR5 act as the primary cell surface receptor and coreceptor; their engagement by viral gp120 results in T cell activation by recruiting p56lck." (PMID 19538732, 2009). "Nevertheless, at proportionately higher concentrations, 191 resembled sCD4, inhibiting HIV-1 infection of CD4+CCR5+ cells and enhancing infection of CD4−CCR5+ cells." (PMID 19343205, 2009). "HIV-1 infection begins with HIV-1 envelope gp120 binding to CD4 and chemokine co-receptors CCR5 (for M-tropic strains) or CXCR4 (for T-tropic strains) on the cell surface of HIV-1 target cells." (PMID 19656383, 2009). "Definition and calculation of components of within population-variability in RNA viral load and CD4 cell count during untreated HIV-1 infection in adults." (PMID 19536329, 2009). "HIV-1 infection was carried out in the presence of high inhibitor concentration (>IC95) to trap CD4-engaged Env in the inhibitor-bound intermediate state." (PMID 19956769, 2009). "Soluble CD4 mimics (SCMs) can exert varied effects on HIV-1 infection of CD4+ and CD4− target cells." (PMID 19343205, 2009). "More recently, an elegant study by Audigé and colleagues has examined the impact of HIV-1 infection on resting CD4+ T cells extracted from ex vivo tonsils." (PMID 19146679, 2009). "In contrast to PBMC cultures, however, HLAC allows a concurrent and prospective experimental analysis of CD4+ T lymphocyte depletion induced by HIV-1 infection." (PMID 19146681, 2009). "We thus decided to run a small-scale study focusing on early transcriptional events following HIV-1 infection in activated primary CD4+ T cells isolated from peripheral blood." (PMID 19146679, 2009). "The impact of host genetic factors on HIV-1 specific CD4+ T cell responses in clade C HIV-1 infection also warrants investigation as different HLA Class I molecules have shown to significantly influence CD8+ T cell responses." (PMID 19352428, 2009). "Higher frequencies of virus-specific CD4+ T cells have been observed in certain individuals who are better able to control HIV-1 infection and in animals persistently infected with live, attenuated strains of SIV." (PMID 19165322, 2009).
HIV-1 infection (continued). "While the effect of HIV-1 on depletion of gut CD4+ T cells in acute HIV-1 infection is well described, we studied blood and tissue B cells soon after infection to determine the effect of early HIV-1 on these cells." (PMID 19582166, 2009). "HIV-1 can infect and replicate in both CD4 T cells and macrophages, however, only CD4 T lymphocytes are depleted during HIV-1 infection." (PMID 19492063, 2009). "In contrast to their loss during progressive HIV-1 infection, CCR5+CD4+ T cells are preserved in individuals who spontaneously control HIV-1 infection and are even increased during the less pathogenic HIV-2 infection." (PMID 19943952, 2009). "This infection model also exhibited CD4 T cell depletion in the animals, a characteristic of chronic HIV-1 infections in humans." (PMID 19674458, 2009). "Case-patients differed from controls in use of other drugs during the previous week, HIV-1 infection, and CD4 count." (PMID 19402961, 2009). "In HIV-1 infection, CD4+ Th1 and Th2 cells play regulatory roles in controlling infection and replication." (PMID 19555490, 2009). "Productive HIV-1 infection of CD4+ T cells in vitro is characterized by formation of multinucleated giant cells, so-called syncytia, which likely results in CD4+ T cell depletion in HIV-1-infected subjects." (PMID 19656383, 2009). "Since SLPI was able to disrupt the association between PLSCR1 and CD4, our data suggest that SLPI inhibits HIV-1 infection by modulating the interaction of the CD4 receptor with PLSCRs." (PMID 19333378, 2009). "The mechanisms involved in the restriction of HIV-1 infection in quiescent CD4+ T-cells remain unidentified." (PMID 19300495, 2009). "First, the sCD4-mediated enhancement of HIV-1 infection of CD4− cells is highly dependent on the level of CCR5 expression." (PMID 19343205, 2009). "We have demonstrated that autophagy is directly responsible for the destruction of uninfected CD4 T cells during HIV-1 infection by X4 strains whereas autophagy is inhibited in X4 HIV-1-infected CD4 T cells and U937 cells." (PMID 19492063, 2009). "For this reason, our group previously derived a CD4 expressing BeWo cell line to study HIV-1 infection." (PMID 19445667, 2009). "It is also based on single cell analyses of the CD4+ T cells undergoing a primary response where R5 HIV-1 infection and the synthesis of CCL4 were largely exclusive." (PMID 18941536, 2008). "HIV-1 infection is characterized by an acute phase of infection where the virus integrates into the host CD4-positive cell genome and establishes an early viral reservoir characterized by a HIV latency in memory CD4+ T cells." (PMID 18597681, 2008). "It is established that acute HIV-1 infection of CD4 T cells results in both NF-κB activation as well as apoptotic cell death." (PMID 18461165, 2008). "Mathematical models have proven useful for the analysis of several aspects of HIV-1 infection including the dynamics of viral replication, the effects of immune responses, and the mechanism of CD4 depletion." (PMID 18171475, 2008). "We present here a mathematical analysis of CD4+ T cell dynamics in the setting of HIV-1 infection in order to explore the dynamics of the latent resting CD4+ T cell reservoir." (PMID 18171475, 2008). "Cell-mediated immune responses involving polyfunctional CD8+ and CD4+ T cells are considered pivotal in the control of human immunodeficiency virus (HIV)-1 infection." (PMID 18416857, 2008). "In this vein, a recent report described the emergence of an unusual CD4+ CD45RA+ CCR7− CCR5+ memory population in infected people that is resistant to HIV-1 infection." (PMID 18941536, 2008). "Although the central focus of HIV-1 pathogenesis has been on the role of CD4+ T-cells, there has been much recent evidence demonstrating the susceptibility of CD8+ T-cells to HIV-1 infection both in vivo and in vitro." (PMID 18923697, 2008).
HIV-1 infection (continued). "Analysis of our model (equations 1–3 in Methods) leads to several predictions about the nature of HIV-1 infection and its impact on CD4+ T cell dynamics." (PMID 18171475, 2008). "Our results clearly reveal that expression of R88-A3G in transduced CD4+ C8166 cells significantly blocked Vif+ HIV-1 infection." (PMID 18414671, 2008). "The major targets of HIV-1 infection are CD4+ T cells and macrophages, as these two cell types express CD4 and CCR5 or CXCR4, the receptor and co-receptor, respectively, for the viral Envelope protein." (PMID 18773076, 2008). "Our data also demonstrate that in the peripheral blood of infected patients, resting CD4 T cells have largely been altered or primed, at least in cofilin activity, to facilitate HIV-1 infection." (PMID 18928553, 2008). "DCs transmit the virus efficiently to CD4 T cells and therefore play an important role in HIV-1 infection." (PMID 18215326, 2008). "Previously, we demonstrated that during HIV-1 infection of resting CD4 T cells, the viral envelope-CXCR4 signaling activates cofilin to overcome the static cortical actin restriction." (PMID 18928553, 2008). "Inhibition of CD4 receptor also explains observed dual inhibition of both X4 and R5-tropic HIV-1 infection, since both strains utilize CD4 as their main receptor." (PMID 18197976, 2008). "The membrane proximal region (MPR) of the transmembrane subunit, gp41, of the HIV envelope glycoprotein plays a critical role in HIV-1 infection of CD4+ target cells and CD4-independent mucosal entry." (PMID 18925934, 2008). "The cellular cytidine deaminase A3G is a powerful innate antiviral factor that restricts HIV-1 infection in resting peripheral blood CD4+ T-lymphocytes." (PMID 18414671, 2008). "The principal conclusion of this report is that CD4+ T cells which secrete anti-viral CCR5 ligands during the primary immune response are ‘self-protected’ from R5 HIV-1 infection." (PMID 18941536, 2008). "HIV-1 infection is characterized by persistent viremia and a progressive decline in both the number and function of CD4+ T cells, including the decrease of LPR to mitogens and antigens and the lack of an effective HIV-1-specific immune response." (PMID 18302775, 2008). "Our studies suggest that HIV specific CD4+ T cells that secrete anti-viral CCL5 ligands should be selectively protected during the primary HIV-1 infection and enter the memory pool." (PMID 18941536, 2008). "Efficacious immune-based therapy in treated chronic HIV-1 infection requires the induction of virus-specific CD4+ T cells and subsequent maturation and maintenance of specific memory CD8+ T cells." (PMID 18976455, 2008). "Acute HIV-1 infection of CD4 T cells often results in apoptotic death of infected cells, yet it is unclear what evolutionary advantage this offers to HIV-1." (PMID 18461165, 2008). "We found that HIV-1/HSV-2 co-infected treatment naïve adults in early HIV-1 infection had higher CD4+ T cell counts than those infected with HIV-1 alone." (PMID 17957262, 2007). "The latent reservoir for HIV-1 in resting CD4+ T cells is the primary known barrier to eradication of HIV-1 infection." (PMID 17784786, 2007). "Here, we showed by in situ investigations that both intraepithelial CD4+ T cells and LC in the human vagina were primary targets of HIV-1 infection." (PMID 17306567, 2007). "Persons with HIV-1/HSV-2 co-infection sustained higher CD4+ T cell counts over time (+69 cells/ul greater (SD = 33.7, p = 0.04) than those with HIV-1 infection alone, after adjustment for HIV-1 RNA levels (−57 cells per 1 log10 higher HIV-1 RNA, p<0.0001)." (PMID 17957262, 2007). "HIV-1 infection enhanced Foxp3 expression in activated CD4+CD25- T cells; which was also abrogated by blockade of endogenous TGF-β." (PMID 17688698, 2007). "Taken together, these findings indicated that pathways of HIV-1 infection in vaginal LC were relatively more complex than in CD4+ T cells." (PMID 17306567, 2007).
HIV-1 infection (continued). "HIV-1 infection profoundly perturbs the immune system and is characterized by depletion of CD4+ T cells and chronic immune activation, which lead to AIDS." (PMID 17465678, 2007). "HIV-1 infection was diagnosed in July 2003 after an episode of cryptococcal meningitis; with a documented CD4+ lymphocyte count of 6 cells/mm3." (PMID 17559655, 2007). "While studying changes in CD4+ memory and naïve T cells during HIV-1 infection, we found that a subset of CD4+ effector memory T cells that are CCR7−CD45RO−CD45RA+ (referred to as TEMRA cells), was significantly increased in some HIV-infected individuals." (PMID 17465678, 2007). "The original observation that magnetic-bead bound CD3 and CD28 antibodies prevent monocytotropic HIV-1 infection of peripheral blood CD4-positive T cells spawned two approaches that were experimentally tested." (PMID 17504532, 2007). "We attempted to augment fully functional HIV-1-specific CD8 and CD4 effector T-cell responses in patients with advanced chronic HIV-1 infection." (PMID 17428345, 2007). "Our investigation of memory T cell subsets during HIV-1 infection led to the discovery of a unique subset of CD4+ T cells called CD4+ TEMRA cells." (PMID 17465678, 2007). "A primary HIV-1 infection system of CD4+ enriched peripheral blood mononuclear cells was utilized to examine the HIV-1 life cycle as a relevant ex vivo system." (PMID 19440453, 2007). "Krzysiek and coworkers found a significant depletion of blood CD4+ T cells expressing α4β7 integrin during primary HIV-1 infection and partial recovery following 48 wk of antiretroviral therapy." (PMID 17147468, 2006). "In HCMV infection, young infants develop mature CD8 T cell responses in the context of low CD4 T cell immune responses whereas in HIV-1 infection CD4 T cell help is integral in controlling HIV-1 infection." (PMID 17183635, 2006). "This is likely due to the presence of densely clustered CCR5+ memory CD4+ T cells at mucosal sites that serve as preferred targets for HIV-1 infection." (PMID 17147468, 2006). "Most recently the anti-retroviral deoxycytidine deaminase APOBEC3G has been shown to strongly protect unstimulated peripheral blood CD4+ T cells against HIV-1 infection." (PMID 16412247, 2006). "Relative resistance of CD4 T cells and/or macrophages to HIV-1 infection has been reported in selected EUs." (PMID 17092330, 2006). "Recent studies of the role of the GI tract have demonstrated that the CD4+ T cells residing in the LP are selectively depleted early in the course of acute HIV-1 infection." (PMID 17147468, 2006). "Strong CD4 T cell resistance to HIV-1 infection is a highly unusual phenomenon and it is reportedly more frequent among EUs." (PMID 17092330, 2006). "Various constitutive mechanisms of CD4 T cell resistance to HIV-1 infection, affecting entry or post-entry steps of viral replication, are associated with resistance to HIV-1 in subjects who remain uninfected despite long-term high-risk behavior." (PMID 17092330, 2006). "In summary, we found low CD4 T cell activation and CCR5 expression as well as a reduced susceptibility to HIV-1 infection in Central African EU partners of HIV-1 infected individuals." (PMID 16792805, 2006). "Only HIV-1 infection and HR-HPV types were statistically significantly associated with HSIL in univariate analysis, while low CD4 cell count (<200 cells μl−1) had an association of borderline significance." (PMID 16832413, 2006). "Overall, the CD4/CD8 ratio had a ≥ 98% sensitivity for diagnosis of infant HIV-1 infection and a specificity ≥ 98%." (PMID 15683549, 2005). "The cytopathic effects of CD4+ MT-2 infection were analysed by optical microscopy assessment of syncytium formation as well as by the HIV-1 infection of cMAGI cells using the Blue Cell Assay." (PMID 15987516, 2005). "During wild-type HIV-1 infection, CD4 and the coreceptors CXCR4 and CCR5 are excluded from the HIV-1 envelope through interactions with HIV-1 Nef protein." (PMID 16371160, 2005).